NPY (neuropeptide Y)
Diseases named in the same sentence as NPY in open-access papers (continued):
Sharing a sentence is not in itself a finding about the gene and the disease.
Anxiety (continued). "The physiological and behavioral effects of NPY are mainly mediated through Y1, Y2, and Y5 receptor subtypes, which are expressed in regions regulating food intake, fear and anxiety, learning and memory, depression, and posttraumatic stress." (PMID 34298907, 2021). "Several stress-related neuropeptides implicated in anxiety, depression and schizophrenia are substrates of DPPIV, including NPY." (PMID 34267682, 2021). "Animal studies have suggested that lower NPY levels are associated with posttraumatic stress disorder (PTSD), depression, and anxiety-like symptoms, and intracerebral NPY administration reduces anxiety and improves mood." (PMID 33670342, 2021). "We previously reported that NPY neurons in the nucleus accumbens (NAc) are involved in the regulation of anxiety behavior." (PMID 34566585, 2021). "In the BLA, NPY neurotransmission has been shown to play a role in modulating anxiety and fear-related behaviors." (PMID 34975380, 2021). "NPY regulates multiple physiological and pathophysiological processes involved in food intake, fear and anxiety, learning and memory, depression, posttraumatic stress, and processing of pain and itch." (PMID 34298907, 2021). "NPY plays an important role in appetite, anxiety state, angiogenesis, and vasoconstriction, and is widely distributed in the central and peripheral nervous systems, especially in the hypothalamus." (PMID 33708805, 2021). "NPY and its Y1 cognate receptor (Y1R) have been shown to be involved in the regulation of stress, anxiety, depression and energy homeostasis." (PMID 34445453, 2021). "Similar brain region-and receptor-specific effects of NPY have been described on social interaction, a test that simultaneously assesses social anxiety-like behavior and social motivation." (PMID 34576305, 2021). "Specific deletion of accumbal NPY neurons by Cre-dependent diphtheria toxin receptor expression in the NAc and systemic diphtheria toxin treatment resulted in anxiety behaviors, as indicated by open field and elevated plus maze tests." (PMID 34298907, 2021). "The NPY receptors in the hippocampus, cerebral cortex, and amygdala are essential for NPY regulation of anxiety, reactivity to stress, cognitive processes, and depression." (PMID 33670342, 2021). "Neuropeptide Y (NPY) is a neural peptide distributed widely in the brain and is well known for its role in appetite, maintenance of energy homeostasis, and anxiety." (PMID 34566585, 2021). "The anxiety condition influenced the density of NPY + cells in the hippocampus, more specifically at the hilus and CA3 regions (Two-way ANOVA, Bonferroni post-hoc test, behavior p < 0.05)." (PMID 34025410, 2021). "It has been postulated that the regulation of central NPY expression is one of the mechanisms of adaptation to chronic stress, which is reflected in the pathophysiology of anxiety and depression." (PMID 33670342, 2021). "The study focused its investigation of the NPY system in areas of the amygdala and extended amygdala that are known to be involved in fear response, anxiety-like behaviors, and ethanol consumption." (PMID 34975380, 2021). "In rats, amygdala-based NPY administration has shown a reduction in anxiety and depressive behaviours, while NPY-knockout mice have been shown to present anxiety and depressive behaviours." (PMID 33670342, 2021). "Previous studies in males demonstrated that intranasal NPY at 150 μg was sufficient to prevent the development of anxiety and depressive-like behavior, however, this was unsuccessful in females." (PMID 34566592, 2021). "Recently, we performed time- and region-specific disruption and chemogenetic activation of NPY neurons in the NAc using NPY-Cre mice, which revealed that NAc NPY neurons have a role in reducing anxiety." (PMID 34566585, 2021). "The acute cold stress-treated NPY-KO zebrafish exhibited anxiety-like behaviours such as remaining stationary and swimming along the side of the tank in the mirror test." (PMID 32246073, 2020).
Anxiety (continued). "In summary, NPY-KO zebrafish exhibited less social behaviour under non-stressful conditions than wild-type fish, whereas under acute stress, they exhibited severe anxiety, similar to NPY-knockout mice and human psychiatric patients." (PMID 32246073, 2020). "Thorsell and colleagues demonstrated that overexpression of NPY conferred resilience to anxiety after restraint stress." (PMID 32867327, 2020). "Genetic models show the NPY system is involved in regulating depressive-like behaviors in both sexes, while its effects on anxiety is more pronounced in males." (PMID 32867327, 2020). "Several studies have shown that NPY is involved in stress related disorders, such as depression, anxiety, and post-traumatic stress disorder (PTSD)." (PMID 33574739, 2020). "NPY-KO animals can be used to study anxiety behaviour over a long time period with physiologically realistic NPY concentrations in vivo." (PMID 32246073, 2020). "NPY is involved in regulating a variety of physiological functions including feeding, circadian rhythm, anxiety, memory, fear, and stress." (PMID 32867327, 2020). "Overexpression or microinfusion of NPY into the hippocampus of male rodents confers resilience to anxiety and conditioned fear after stress." (PMID 32867327, 2020). "We found that NPY-KO zebrafish under acute stress exhibited freezing accompanied with an upregulation of th1 and th2, suggesting the involvement of catecholamines in NPY-KO anxiety behaviour." (PMID 32246073, 2020). "Intranasal NPY effectively reversed hyperarousal, depressive-like and anxiety behavior seen in vehicle-treated animals when it was given a week or more after exposure to stress." (PMID 32867327, 2020). "NPY has gained attention as an anti-stress peptide, it promotes resilience to stress and reduces behaviors relevant to anxiety in vivo." (PMID 33192369, 2020). "Overall, this novel wearable NPY biomarker tracking system is envisioned to be a chronic anxiety and MDD management platform via self-monitoring." (PMID 35520310, 2020). "Some studies have also shown that SST and NPY have significant anti-anxiety effects, with a prominent involvement of the amygdalar circuitry." (PMID 32765318, 2020). "NPY-KO zebrafish exhibited several anxiety-like behaviours, such as a decrease in social interaction in mirror test and decreased locomotion in black-white test." (PMID 32246073, 2020). "Knock out animals and Flinders genetic models show that NPY is important for attenuating depression in both sexes, while its effects on anxiety appear more pronounced in males." (PMID 32867327, 2020). "Novel wearable NPY biomarker tracking system, envisioned to be a chronic anxiety and MDD management platform via self-monitoring." (PMID 35520310, 2020). "In the present study, we examined the associations of NPY, PYY, and PP plasma levels with anxiety, depressiveness and perceived stress in obese patients." (PMID 33192409, 2020). "Administration of intranasal NPY shortly before stress exposure (prophylaxis) prevented the development of depressive-like behavior, anxiety and hyperarousal." (PMID 32867327, 2020). "According to previous studies, exercise exerted anti-anxiety effects by improving hippocampal neurogenesis and normalizing the neurotransmission of neuropeptide Y (NPY)." (PMID 33329133, 2020). "Several rodent models have been used to study the mechanism underlying NPY-related psychiatric disorders, and the observed phenotypes are similar to those of human anxiety; as a result, NPY and its receptors have been targeted for depression therapy." (PMID 32246073, 2020). "Another gene of relevance to traumatic stress and resilience is the neuropeptide Y (NPY) gene, which is expressed in a number of brain regions and plays a key role in the regulation of fear, stress, anxiety, learning, and memory." (PMID 33362593, 2020). "In contrast, NPY KO in males displayed greater anxiety-like behavior on all these measures as compared to WT controls." (PMID 32867327, 2020).
Anxiety (continued). "But how does NPY balance energy homeostasis with fear‐ and anxiety‐related behaviors and which other neuropeptides are directly or indirectly involved?" (PMID 31271235, 2019). "We investigated the immunohistochemical alterations of the hippocampal neuropeptide Y (NPY) and melanocortin 4 receptor (MC4R) neurons, as a possible underlying mechanism in a modulation of anxiety-like behavior in rats." (PMID 30863280, 2019). "It has been noticed that serum levels of NPY were lower in patients with depression and anxiety symptoms." (PMID 30863280, 2019). "The increase in serum NPY in the combined groups was also accompanied with a clear decrease of anxiety-like manifestations compared to the sedentary AASs groups." (PMID 30863280, 2019). "Collectively, NPY unequivocally increases food intake and reduces fear and anxiety by activating Y1Rs." (PMID 31271235, 2019). "Rodent studies have provided numerous evidences proving the relation between NPY and PV neurons, and anxiety." (PMID 31281833, 2019). "It has been shown that the activity of PV+ and NPY+ interneurons plays a role in maintaining normal cognitive function, circadian rhythms, food intake, and anxiety." (PMID 31281833, 2019). "NPF is the Drosophila counterpart of mammalian NPY, which regulates feeding, reproduction, aggression, anxiety, depression and the alcohol addiction (Nässel and Wegener, 2011)." (PMID 31403399, 2019). "The relationship between NPY hippocampal immunoreactivity and anxiety behavior in our study was confirmed by strong (also positive) correlation between the total number of NPY per hippocampal section and CDOA." (PMID 30863280, 2019). "A recent clinical trial demonstrated high-dose intranasal NPY can reduce self-reported anxiety levels in PTSD patients." (PMID 30804766, 2019). "This suggests a differential role of GABA release from NPY+ cells in regulating anxiety in adolescents compared to adults, highlighting the need for further study of the differential roles of GABA released from NPY+ cells in development." (PMID 30024942, 2018). "Acupuncture at PC6 reduces chronic corticosteroid-induced depression- and anxiety-like behavior via modulation of NPY expression levels." (PMID 29643431, 2018). "They showed different anxiety behavior, and on study with human, individuals with anxiety showed different levels of NPY plasma levels, especially higher." (PMID 31435520, 2018). "A previous study showed that knockdown of Gad1 from NPY+ cells led to reduced anxiety behaviors in adult mice." (PMID 30024942, 2018). "Neuropeptide Y (NPY) interneurons are a subset of GABAergic interneurons that also are found abundantly in brain regions related to anxiety behavior such as hippocampus, prefrontal cortex, and amygdala." (PMID 30024942, 2018). "Lesioning a subgroup of interneurons, of which a large portion were NPY+ cells, has been shown to increase anxiety-like behaviors in mice." (PMID 30024942, 2018). "One class of GABAergic interneurons, Neuropeptide Y (NPY) expressing cells, is abundantly found in brain regions associated with anxiety and fear learning, including prefrontal cortex, hippocampus and amygdala." (PMID 30024942, 2018). "This study sought to determine the importance of GABA release from NPY+ cells in anxiety in adolescent animals." (PMID 30024942, 2018). "Despite this clear behavioral differentiation, the expression of NPY in three well-known areas involved with anxiety- and depressive-like behaviors was altered by maternal deprivation on both periods of development and in both sexes." (PMID 30131681, 2018). "Here we used the NPYGAD-TG mice to test the importance of GABA release from NPY+ interneurons on anxiety and other behaviors in adolescent male and female mice (1–2 months old)." (PMID 30024942, 2018). "Both intracerebroventricular administration of NPY and genetic overexpression of NPY in the hippocampus decreased anxiety levels in rats, while NPY knockout mice displayed increased anxiety in an open field." (PMID 29377906, 2018).
Anxiety (continued). "When NPY is administered to animals exposed to a neurodegenerative stress (e.g., PTSD or Alzheimer’s disease), attenuation of anxiety and memory loss has been reported." (PMID 28161798, 2017). "In particular, those expressing parvalbumin (PV) or neuropeptide Y (NPY) have demonstrated a role in both anxiety and memory." (PMID 28138095, 2017). "Within the mammalian CNS, NPY receptor subtypes are expressed in regions overlapping with NPY expression and involved in regulation of anxiety and stress, depression, energy homeostasis, and memory function." (PMID 28824541, 2017). "The amygdala is a central neurobiological substrate for mediation of stress- and anxiety-related behaviors and has strong NPY-ergic innervation." (PMID 28824541, 2017). "An infusion of NPY into the central nucleus of the amygdala in alcohol-preferring rats normalizes both anxiety behaviors (assessed using the light/dark box exploration test) and alcohol intake." (PMID 28824541, 2017). "In this review, we present an overview of findings with regard to the NPY system in relation to anxiety and stress, acute as well as chronic; furthermore we discuss post-traumatic stress disorder and, in part depression." (PMID 28824541, 2017). "As far as other epigenetic mechanisms, histone acetylation has been shown to affect anxiety-related behavior as well as NPY expression within the amygdala." (PMID 28824541, 2017). "In a study with patients with depression and anxiety, serum NPY levels were lower in the patients than in the controls." (PMID 28824541, 2017). "Another early finding, the prevention of formation of gastric erosions, also indicated a role of NPY in regulation of stress-related events and, possibly, anxiety-related behavior." (PMID 28824541, 2017). "Specifically, more pronounced deficits in histone acetylation were suggested to be involved in lower NPY expression in the amygdala of P rats, and, thereby, operative in controlling anxiety-like and alcohol-drinking behavior." (PMID 28824541, 2017). "This was also confirmed by the finding that rats with an innate higher number of NPY-positive cells in the central amygdala displayed less anxiety-like behavior in the light–dark box model." (PMID 28824541, 2017). "Some lines of alcohol-preferring rats also exhibit higher anxiety-like behaviors and lower amygdala NPY levels." (PMID 28824541, 2017). "In this regard, to get a better understanding of the potential mechanisms underlying the anxiety effects that were observed, we analyzed the CRF and NPY signals in these regions." (PMID 28223925, 2017). "Recently, studies in clinical investigations and rodent models have demonstrated the role of NPY and its receptors in mediating fear, anxiety and PTSD." (PMID 26016844, 2015). "Observed the up-regulation of Y2 receptor mRNA and reactive behavior during predator exposure and anxiety-like behavior of LTSC mice are consistent with the Y2 receptor-mediated anxiogenic action of NPY." (PMID 26016844, 2015). "NPY expression helps to inhibit anxiety, and genetic variations in the expression of NPY modulate emotion and stress response." (PMID 25161819, 2014). "Like NPY’s effect on anxiety, its hemodynamic effects are also in contrast to CRF; central administration of NPY lowers blood pressure and heart rate at rest and in response to social defeat in rats." (PMID 25206349, 2014). "This review highlights proinflammatory cytokines, CRF, and NPY systems amongst those capable of generating both depressive or anxiety-like behaviors and reductions in HRV, thereby increasing CVD risk." (PMID 25206349, 2014). "Elevated NPY levels have also been associated with resistance to an anxious phenotype; in rats characterized as exhibiting high or low levels of anxiety, NPY mRNA in the amygdala was negatively correlated with anxious behavior." (PMID 25206349, 2014).
Anxiety (continued). "Other neuropeptides are also responsible for modifying the activity of neural circuits related to motivation, such as neuropeptide S (NPS) and NPY, which influence arousal, stress, reward, memory, and reduce anxiety." (PMID 24782729, 2014). "In the brain, NPY is one of the most abundant neuropeptides, playing a role in many brain functions such as stimulation of food intake, reduction of anxiety as well as improvement of stress coping and cognition." (PMID 25414650, 2014). "We assessed levels of the Neuropeptide-Y1 Receptor (NPY1R) in the frontal cortex based on the demonstrated role of NPY on anxiety-like behavior." (PMID 23483949, 2013). "Hypothalamic NPY is a highly conserved neuropeptide that contributes controlling daily feeding behavior, energy homeostasis, stress, and anxiety." (PMID 24225225, 2013). "Several neuropeptides (neuropeptide Y, isotocin, urocortin 3, prolactin) showed consistent expression patterns with the alleviation of stress and anxiety when anxiety-related behavior was reduced with fluoxetine treatment." (PMID 23706039, 2013). "While Y1R has generally been shown to mediate many of the anxiolytic and anti-drinking effects of NPY, Y2R has been shown to increase anxiety and alcohol consumption." (PMID 24399943, 2013). "Neuropeptide Y is a 36-amino-acid polypeptide with powerful anxiolytic-like properties in various animal models of anxiety and stress." (PMID 23761766, 2013). "Many studies on animal models and humans have confirmed the beneficial role of NPY in mediating resilience and vulnerability to stress and anxiety." (PMID 23422934, 2013). "Classically, NPY actions at postsynaptic Y1R decrease anxiety, depression, and alcohol drinking, while its actions at presynaptic Y2R produce the opposite behavioral phenotypes." (PMID 24399943, 2013). "In the amygdale, evidence has shown that decreased expression of the NPY gene is related to the increased anxiety and alcohol intake and that c-Fos immunoreactivity is increased after the administration of anxiogenic drugs." (PMID 24225225, 2013). "Genetic and pharmacological manipulations of central NPY have shown that this peptide plays an important role in anxiety, depression, and alcohol drinking behavior." (PMID 24399943, 2013). "Conversely, it has also been shown that a reduction of this activity, for example via activation of inhibitory neuropeptide Y-expressing neurons, leads to a reduction in anxiety-like behavior." (PMID 23071554, 2012). "NPY has anxiety-reducing properties in rodents and is thought to enhance resilience to stress in humans." (PMID 23584116, 2012). "Several findings point to a role for NPY produced in the body (i.e., endogenous NPY) in the control of stress- and anxiety-related behaviors, supporting the antistress effects observed following central administration of NPY." (PMID 23584117, 2012). "In animal models, acute physical restraint, which promotes experimental anxiety, suppresses NPY expression within the amygdala and cortex, an effect that parallels the anxiety-inducing effects of stress." (PMID 23584117, 2012). "The action of BDNF has been linked to molecules important for the control of brain energy metabolism and anxiety-like behaviors such as neuropeptide Y (NPY) and glucocorticoid receptor (GR)." (PMID 22163304, 2011). "For example, in addition to anxiety and stress, NPY and GR have been involved in regulation of energy balance and appetite." (PMID 22163304, 2011). "The anxiety-reducing effects of NPY and the anxiety-enhancing effects of antagonists of NPY receptors are fairly well-documented, providing strong evidence for NPY's role in modulating anxiety responses." (PMID 22163304, 2011). "Recently, we have shown that trichostatin A (TSA), an HDAC inhibitor, can prevent alcohol withdrawal-related anxiety, while restoring histone acetylation levels and neuropeptide Y (NPY) expression in the amygdala of rats." (PMID 21593965, 2008).